ANKRD2 (ankyrin repeat domain 2)
Description:
Functions as a negative regulator of myocyte differentiation. May interact with both sarcoplasmic structural proteins and nuclear proteins to regulate gene expression during muscle development and in response to muscle stress.
Synonyms: ARPP
Tractability: No criterion of Open Targets' tractability assessment is met for any kind of drug.
Gene: Protein-coding gene on chromosome 10 (97,572,499 to 97,583,896, forward strand). Ensembl gene ENSG00000165887.
Subcellular location: Cytoplasm, myofibril, sarcomere, I band; Cytoplasm, cytosol; Nucleus; Nucleus, PML body
Subcellular location (Human Protein Atlas): Vesicles
Gene Ontology:
Molecular function: protein binding; protein kinase B binding; RNA polymerase II-specific DNA-binding transcription factor binding; structural constituent of muscle
Biological process: negative regulation of myoblast differentiation; negative regulation of transcription by RNA polymerase II; regulation of transcription by RNA polymerase II; muscle contraction; muscle organ development; regulation of gene expression
Cellular component: cytosol; nucleus; euchromatin; I band; PML body
Genetic constraint (gnomAD): Loss-of-function variants: 36 observed, 33.33 expected, observed/expected ratio (o/e) 1.08, 90% interval 0.83 to 1.43. The upper end of that interval is the gene's LOEUF score, 1.43, which puts it in group 5 of 6, group 1 being the genes least tolerant of losing a copy. Missense variants: 405 observed, 402.09 expected, observed/expected ratio (o/e) 1.01, 90% interval 0.93 to 1.09. Synonymous variants: 156 observed, 164.51 expected, observed/expected ratio (o/e) 0.95, 90% interval 0.83 to 1.08.
Homologues: Orthologues: chimpanzee ANKRD2 (99% identical), macaque ANKRD2 (96% identical), dog ANKRD2 (91% identical), rabbit ANKRD2 (91% identical), pig ANKRD2 (89% identical), mouse Ankrd2 (89% identical), rat Ankrd2 (88% identical), guinea pig ANKRD2 (87% identical), tropical clawed frog ankrd2 (59% identical), zebrafish ankrd2 (46% identical). Paralogues in human: ANKRD1 (42% identical).
Diseases named in the same sentence as ANKRD2 in open-access papers:
ANKRD2 is named in the same sentence as 38 diseases in open-access papers, as found by Europe PMC text mining. Sharing a sentence is not in itself a finding about the gene and the disease. The quoted sentences say what the papers report.
dilated cardiomyopathy (5 papers, 2014 to 2025). Cardiomyopathy which is characterized by dilation and contractile dysfunction of the left and right ventricles. "ANKRD2 was detected in the adult human heart and has been determined to be up-regulated in human dilated cardiomyopathy." (PMID 34003819, 2021). "Apart from altered expression in skeletal muscle disorders, Ankrd2 was found upregulated in dilated cardiomyopathy patients." (PMID 31428229, 2019). "Ankrd2 upregulation in some human dilated cardiomyopathies and congenital myopathies might be also related to an altered response to mechanical strain, as well as to altered levels of ROS reported in these disorders, as a consequence of increased muscle damage and regeneration." (PMID 31428229, 2019). "Despite the striking expression pattern in the heart and skeletal muscle, and possible association with diseases such as cardiac hypertrophy, dilated cardiomyopathy, skeletal muscle myopathy and muscular dystrophy, physiological roles of CARP and ANKRD2 remain unclear." (PMID 26398569, 2015). "Furthermore, Ankrd2 was found to be upregulated in human dilated cardiomyopathy, suggesting that Ankrd2 may also be involved in cardiac pathologies." (PMID 24736439, 2014). "Reports surrounding the role of ANKRD2 gene are limited, although a recent study demonstrated that ANKRD2 may be involved in human HCM and dilated cardiomyopathy pathways." (PMID 40609041, 2025).
cardiomyopathies (3 papers, 2011 to 2019). "One of the promising lines of future studies on Ankrd2 could be to identify mutations in Ankrd2 gene that are linked to these cardiomyopathies as has been done for Ankrd1/CARP." (PMID 22016770, 2011). "Moreover, altered expression of Ankrd2 was detected in myopathies, cardiomyopathies, and some tumors." (PMID 31428229, 2019). "Being a part of a macromolecular mechanosensory complex, it has been shown to play a role in cardiomyopathies via their interaction with genes such as MLP (muscle LIM protein), MYOZ2 (myozenin 2), ANKRD2 (ankyrin repeat domain 2), and sAnk1 (small muscle-specific ankyrin 1)." (PMID 31426609, 2019).
diabetes (3 papers, 2012 to 2022). "At the same time, studies in a diabetic mouse model showed that the expression level of ANKRD2 was also changed in diabetes." (PMID 36613828, 2022). "For example, high expression of Pla2g5 and/or Prl5a1, as well as low expression of Ankrd2 and/or Pappa2, indicates exposure to diabetes, while low expression of Kcnk2 and/or Mmp13 indicates exposure to breeder diet." (PMID 22701643, 2012). "A compensatory mechanism of FAK and Ankrd2 may ensure the muscle hypertrophic responses even in catabolic conditions such as diabetes." (PMID 26197932, 2015).
head and neck squamous cell carcinoma (3 papers, 2020 to 2025). A squamous cell carcinoma that arises from any of the following anatomic sites: lip and oral cavity, nasal cavity, paranasal sinuses, pharynx, larynx, and salivary glands. "Interestingly, data from the TCGA (GDC DataPortal) repository revealed a significant association between low ANKRD2 expression and improved overall survival in head and neck squamous cell carcinoma (HNSC), lung adenocarcinoma (LUAD), and uveal melanoma (UVM)." (PMID 40004199, 2025). "A recent study performed in head and neck squamous cell carcinoma (HNSCC) has presented Ankrd2 as a negative regulator of the progression of this cancer." (PMID 33419058, 2021).
cardiac hypertrophy (2 papers, 2014 to 2015). "It is well known that CARP, Ankrd2, and DARP are upregulated in response to stress such as cardiac hypertrophy." (PMID 24736439, 2014).
osteosarcoma (2 papers, 2021 to 2025). A usually aggressive malignant bone-forming mesenchymal neoplasm, predominantly affecting adolescents and young adults. "Strikingly, the loss of Ankrd2 enhances the sensitivity of osteosarcoma cells to doxorubicin and cisplatin, highlighting Ankrd2 potential as a therapeutic target to improve chemotherapeutic efficacy." (PMID 40004199, 2025). "This study investigates the functional role of Ankrd2 in osteosarcoma cells, revealing its critical involvement in cell proliferation and response to chemotherapeutic drugs." (PMID 40004199, 2025). "Our observations further revealed that OS cells devoid of Ankrd2 showed an increased sensibility to doxorubicin and cisplatin, two of the most common chemotherapeutic drugs used in the treatment of osteosarcoma and other malignancies." (PMID 40004199, 2025). "As a whole, our data present Ankrd2 as a novel player in osteosarcoma development, opening up new therapeutic perspectives." (PMID 33419058, 2021). "In this paper, we report that Ankrd2 is expressed in cell lines obtained from human osteosarcoma and demonstrate a contribution by this protein in the pathogenesis of this insidious disease." (PMID 33419058, 2021). "Ankrd2 involvement in osteosarcoma development was evaluated in clones of Saos2, U2OS, HOS and MG63 cells stably expressing Ankrd2, through the investigation of hallmark processes of cancer cells." (PMID 33419058, 2021). "By subjecting human osteosarcoma cell lines expressing or silencing Ankrd2 to several functional assays, our results demonstrated that Ankrd2 is involved in the pathogenesis of this cancer." (PMID 33419058, 2021). "In the study presented here, we report on Ankrd2 basal expression in cell lines derived from human osteosarcoma and demonstrate for the first time that the modulation of the level of expression of Ankrd2 affects certain oncogenic properties of these cells." (PMID 33419058, 2021). "Since both myocytes and osteoblasts are mesenchymal-derived cells, we were interested in examining the role of Ankrd2 in the progression of osteosarcoma which features a mechano-stress component." (PMID 33419058, 2021). "Therefore, the main aim of our study has been to investigate the mechanistic role of Ankrd2 in tumor cells’ progression upon Ankrd2 deprivation, using osteosarcoma-derived cell lines." (PMID 40004199, 2025). "On the contrary, the depletion of Ankrd2, by blocking the final downstream effects of multiple signaling cascades, might impair in a more unambiguous way the fate of osteosarcoma cells." (PMID 33419058, 2021). "Although specific roles for Ankrd2 in bone physiology have not been described yet, based on its involvement in cell proliferation and mechanotransduction, as well as on its interaction with oncogenes, we hypothesized that Ankrd2 may play a role in osteosarcoma." (PMID 40004199, 2025).
rhabdomyosarcoma (2 papers, 2011 to 2021). A rare aggressive malignant mesenchymal neoplasm arising from skeletal muscle. "Other studies have in parallel described an increased expression of Ankrd2 in cells and tissues derived from some primary tumors, such as rhabdomyosarcoma and renal oncocytoma." (PMID 33419058, 2021). "In fact, the expression of Ankrd2 is elevated in a very high percentage of rhabdomyosarcomas and its use as a potential tumor marker for differential diagnosis of this soft tissue sarcoma has been suggested." (PMID 22016770, 2011).
bladder urothelial carcinoma (1 paper, 2021). "Interestingly, a homolog of Ankrd2, Ankrd23 was recently identified as a potential dual-role cancer driver gene acting as an oncogene in renal clear-cell carcinoma, and a tumor suppressor in bladder urothelial carcinoma." (PMID 33419058, 2021).
muscular disease (1 paper, 2019). Myopathy is a peripheral nervous system disease consisting of any abnormal condition or disease of the muscular tissues; commonly designates a disorder involving skeletal muscle. "Interestingly, in vitro studies have demonstrated that point mutations in the ZASP6 gene causative for a muscular disease called ZASPopathy prevented ZASP6 interaction with Ankrd2, opening the question of Ankrd2 involvement in the pathophysiology of this myofibrilar myopathy." (PMID 31428229, 2019).
spinal muscular atrophy (1 paper, 2011). A motor neuron disease that affect the muscles, and characterized by muscle weakness and atrophy resulting from progressive degeneration and irreversible loss of the anterior horn cells in the spinal cord (i.e., lower motor neurons) and the brain stem nuclei. "In spinal muscular atrophy Ankrd2 is induced in hypertrophic myofibers and Ankrd2–positive myofibers are arranged in groups as a result of the process of denervation." (PMID 22016770, 2011).
type 2 diabetes (1 paper, 2011). "It is interesting that one of the pathways affected by Ankrd2 silencing is the Insulin signaling pathway especially since DARP, a MARP family member, is up regulated in type 2 diabetes and thought to have a role in glucose uptake in muscle." (PMID 22016770, 2011).
tumor (5 papers, 2011 to 2025). "In the future, the evaluation of the Ankrd2 expression level in cells from a cohort of primary and metastatic OS will assist in ascertaining if Ankrd2 basal expression in OS correlates with tumor grade and severity of the disease." (PMID 33419058, 2021). "The opposing effects exhibited by Ankrd2 in OS cells and in HNSCC hint at a role of Ankrd2 as a “double-faced” cancer gene, a well-documented peculiarity of certain genes exhibiting oncogenic or tumor-suppressor behavior depending on the biological context." (PMID 33419058, 2021). "This positive correlation of VENTXP1 and ANKRD2 expression was further confirmed in HNSCC tumor samples, VENTXP1-overexpressed xenografts, and in HNSCC cell lines." (PMID 33037177, 2020). "Defining a novel mechanistic role for Ankrd2 in promoting tumor progression, we propose that Ankrd2 reduction could be exploited as an adjuvant strategy to enhance the efficacy of chemotherapy, offering new therapeutic opportunities for OS treatment." (PMID 40004199, 2025). "The findings on the permissive role of Ankrd2 in spheroid formation and in the modulation of MMP2 and MMP9 activities, as well as the evidence that Ankrd2-depleted clones lose the ability to form spheroids, hint at a positive role for Ankrd2 in triggering metastases and tumor spreading." (PMID 33419058, 2021). "Despite being detected in tumor cells and tumor tissues, any role of Ankrd2 in OS development, maintenance and progression has not been described so far ever described any role of Ankrd2 in OS development, maintenance and progression." (PMID 33419058, 2021).
cancer (4 papers, 2013 to 2025). A tumor composed of atypical neoplastic, often pleomorphic cells that invade other tissues. "Ankrd2, a mechanoresponsive protein primarily studied in muscle physiology, is emerging as a player in cancer progression." (PMID 40004199, 2025). "Further comprehensive studies using patient samples or patient-derived xenograft models will be essential to determine the clinical relevance of Ankrd2 in OS and other cancers." (PMID 40004199, 2025). "Albeit the general interest in exploring the contribution of Ankrd2 to cancer progression is growing, the definition of its role in cancer cells is still incomplete." (PMID 40004199, 2025). "According to the authors, Ankrd2 is involved in the block of cancer cell proliferation by directly inhibiting the NF-κB signaling pathway." (PMID 33419058, 2021). "Altogether, these findings allowed us to suppose that Ankrd2 has a permissive role in cancer progression." (PMID 33419058, 2021). "Hopefully, a thorough investigation of the Ankrd2 interactome in different types of cancers will help us to explain the controversial role of Ankrd2 in cancer progression." (PMID 33419058, 2021). "Abnormal expression of the ANKRD2 gene leads to neuromuscular disorders, cardiovascular diseases, and even cancer." (PMID 24244196, 2013). "Furthermore, the efficacy of chemotherapeutics was significantly improved upon Ankrd2 reduction, suggesting new therapeutic approaches for the treatment and the cure of cancer cells." (PMID 40004199, 2025). "This suggests that Ankrd2 may have potential as a prognostic biomarker in certain cancers and warrants further investigation." (PMID 40004199, 2025). "Nonetheless, due to observations obtained by other studies in other model systems, our findings also suggest that Ankrd2 might behave as a “double-faced” cancer driver gene." (PMID 33419058, 2021). "Since MMP2 and MMP9 are two of the most characterized MMPs in cancer metastasis, and since Ankrd2 modulates cell motility, we tested the possibility that Ankrd2 might promote invasion by modulating the activity of these MMPs." (PMID 33419058, 2021). "Nonetheless, we have also observed that Ankrd2 silencing had a negative impact on cancer cells progression." (PMID 33419058, 2021). "Suggesting that Ankrd2 might have a role in supporting cancer progression, our findings demonstrated that it was not the overexpression rather the absence of Ankrd2 that had remarkable effects on the pathophysiology of OS cells." (PMID 40004199, 2025).
muscular disorder (2 papers, 2019 to 2024). "ANKRD2 is not necessary for life, nor is it the direct cause of any muscular disorder, and multiple lines of evidence suggest that an anomalous expression level of ANKRD2 might contribute to a muscular phenotype." (PMID 37946414, 2024).
cardiac diseases (1 paper, 2011). "Apart from tumors, Ankrd2 could be linked to dystrophies and cardiac diseases since some proteins from the FATZ (myozenin/calsarcin), myotilin and Enigma families are differentially expressed in Ankrd2 silenced myotubes." (PMID 22016770, 2011).
genetic diseases (1 paper, 2025). "The involvement of Ankrd2 in modulating lamin A expression is presented here for the first time, and might have a significant impact considering that lamin A plays a crucial role in genetic diseases affecting skeletal muscle, in physiological aging, and in several types of malignancies." (PMID 40004199, 2025).
ANKRD2 also shares sentences with these, for which no sentence is quoted: breast carcinoma (2 papers); Atrophy (1); cardiovascular diseases (1); colorectal cancer (1); congenital myopathies (1); Emery-Dreifuss muscular dystrophy (1); esophageal carcinoma (1); Hyperglycemia (1); lung adenocarcinoma (1); lung carcinoma (1); muscular dystrophy (1); myopathy (1); ovarian carcinoma (1); primary immunodeficiency (1); prostate carcinoma (1); renal clear-cell carcinoma (1); renal oncocytoma (1); skeletal muscle disorder (1); soft tissue sarcoma (1); tibial muscular dystrophy (1); uveal melanoma (1); ZASPopathy (1).